IL6 (interleukin 6)
Diseases named in the same sentence as IL6 in open-access papers (continued):
Sharing a sentence is not in itself a finding about the gene and the disease.
infection (continued). "The wild-type genotype of the IL6-174G/C polymorphism seems to be a factor that contributes to the infection of HCV, because in addition to being associated with increased IL-6 levels, it was also related to increased viral load." (PMID 35336914, 2022). "Tumor Necrosis Factor- α (TNF-α) and IL-6 concentrations were significantly higher during the acute phase of infection compared to HD." (PMID 35456119, 2022). "Six hours post-infection, we detected a significant increase in IL-6 and IL-8 secretion in cells infected with PA14." (PMID 35508983, 2022). "Although IL-6 level in co-infected NHL patients was significantly higher than non-infection patients and healthy people." (PMID 35463642, 2022). "Elevated IL-6 levels during the period of infection or tissue damage can lead to the development of serious complications, while persistent IL-6 expression can induce the onset of chronic inflammatory diseases." (PMID 35336914, 2022). "The results confirmed previous flow cytometry data obtained using CBA kit, which showed an early increase in TNF-α in the immunized groups and significantly higher levels of IL-6 in the group immunized with the hybrid within the first six hours of infection." (PMID 36477013, 2022). "Regarding A549, increased production of IL-6 was observed at 48 h after infection with H1N1, and an increased production of MIP-1α was observed at 72 h; combined treatment with alloferon and zanamivir resulted in suppression of both." (PMID 36614125, 2022). "In fact, the genes encoding proinflammatory cytokines IL-1α, IL-6, TNF-α, and IL-8 are strongly downregulated compared to infection with H. pylori alone." (PMID 36394050, 2022). "CRP gene transcription is initiated in response to tissue damage, infection, or proinflammatory cytokines such as interleukin-6 (IL-6) and tumor necrosis factor (TNF)." (PMID 35821205, 2022). "Serum cytokine IL-6 is a useful biomarker to differentiate bacterial and other pathogen infection, which can be integrated with mNGS to improve its diagnostic ability for the microbiological etiology of febrile diseases." (PMID 35391735, 2022). "During the acute inflammatory response in the early phase of tissue injury or infection, IL-6 promotes the removal of damaged tissue or infected cells." (PMID 35573242, 2022). "It was reported that mice with intact IFN-γ but a deficiency in IL-6 and TNF-α all succumbed to MTB after infection." (PMID 35265079, 2022). "IL-6 is a pleiotropic cytokine involved in the onset and resolution of inflammation and responses to infection, tissue remodelling, and cancer." (PMID 35615531, 2022). "Compared with the control, the expression levels of TNF-α (P < 0.01), IL-1β (P < 0.001) and IL-6 (P < 0.001) were significantly increased at 1 week after infection." (PMID 36171756, 2022). "IL-6 displays both pro- and anti-inflammatory effects, notably mediating the acute phase response to infection." (PMID 35204231, 2022). "By contrast, the TNF-α and IL-6 levels in hcp1MVs- and hcp1MVs/adjuvant-immunized mice five days postchallenge decreased continuously after day 0.5 of infection (except TNF-α)." (PMID 36618368, 2022). "During the inflammatory period, macrophages secrete pro-inflammatory factors (IL-1β, TNF-α, IL-6, etc.)and anti-inflammatory factors (IL-10) to clear the necrotic tissue and prevent infection at the wound site." (PMID 35877710, 2022). "These pro-inflammatory cytokines were also found to be upregulated in CSF during infection, and IL-6 also in serum." (PMID 35788177, 2022). "BBV152-treated macaques showed normal post-infection oxygen saturation (SpO2), lower levels of pro-inflammatory cytokine IL-6, and protection against post-infection CD8 T-cell lymphopenia." (PMID 36177016, 2022). "The principal cytokines released by the host on infection include pro-inflammatory cytokines such as interleukin (IL)-1, IL-6, and tumor necrosis factor (TNF)." (PMID 35698506, 2022).
infection (continued). "IL-6 is secreted by Th2 cells and macrophages to stimulate immune response during infection and after trauma, leading to inflammation." (PMID 36317105, 2022). "Elevated activity of IL-1β and IL-6 cytokines has been observed at the nasopharynx region, which is the key site of infection where higher bioactivity of IL-6 is strongly correlated with a higher load of SARS-CoV-2." (PMID 36298704, 2022). "The transcriptional analysis of pulmonary inflammatory genes (including Il1b, Ifng, Il6, and Tnf) 3 days after infection with the different passages revealed a progressively increasing inflammatory response." (PMID 35023830, 2022). "In the early stage of infection, classically activated macrophages can produce a group of proinflammatory cytokines such as interleukin 6 (IL-6), IL-12, and tumor necrosis factor alpha (TNF-α)." (PMID 35328497, 2022). "In response to tissue damage and infection, IL-6 is immediately and transiently produced by various cells, including fibroblasts, vascular endothelial cells, mast cells, macrophages, T cells, and B cells." (PMID 35469194, 2022). "Zinc supplementation studies have shown decreased oxidative stress due to its participation in free radical scavenging and pro-inflammatory markers levels such as IL-1, IL-6 and TNFα, even during infection." (PMID 36138753, 2022). "IL-6 displays pleiotropic effects with pro-inflammatory and ant-inflammatory activities responsive to tissue damage and infection by a context-dependent pattern." (PMID 36290585, 2022). "Cytokines in the brain (TNF-α, CCL-2, CXCL-2, CXCL-10, IL-1β, IL-6, IL-17, and M-CSF) were upregulated after infection at 3 dpi, and the cytokine content gradually decreased with extension of the infection time." (PMID 36352407, 2022). "IL-6 is very important in the early immune response to infections and mediates the uncontrolled production of chemokines and cytokines." (PMID 36287506, 2022). "IL-6 is primarily a pro-inflammatory cytokine-mediated by trans-signaling during an infection; it is also responsible for many immunoregulatory and anti-inflammatory activities mediated by classical signaling." (PMID 35276864, 2022). "Quantitative analysis of proteins secreted into the media from infected HLOs showed a significant increase in IL-6 secretion as early as 48 h post-infection." (PMID 36128218, 2022). "In contrast, IL-6 and granulocyte-colony stimulating factor (G-CSF) were decreased significantly at 12 and 24 h post-infection with GlfT2_KD." (PMID 36090984, 2022). "To determine the primary cellular source of the late IL‐6 appearing after an N67C infection, we isolated pDCs, macrophages, and cDCs from WT mice at different time points after N67C infections." (PMID 35635376, 2022). "The pro-inflammatory cytokines upregulated during infection include IL-6 and TNF-α, and highly upregulated chemokines MIP-1α, MCP-1, and RANTES." (PMID 36071442, 2022). "IL6 was also elevated at baseline in aged mice compared to controls but did further increase upon infection." (PMID 35798721, 2022). "Infection with either virus also resulted in an induction of the pro-inflammatory genes CXCL8 (encoding IL-8), IL6 and TNF, albeit to a lesser extent in SARS-CoV-2-infected cells." (PMID 35840680, 2022). "In children with hematological malignancies, greater expression levels of IL-6 and IL-10 predict infection, and their high expression indicates the severity of the infection." (PMID 35463642, 2022). "It is worth mentioning that along with the infection progression (weeks 7 and 11) we observed a gradual decrease in the influence of IL-6 from B-cells onto T cell response against mycobacteria." (PMID 35154093, 2022). "A pleiotropic cytokine, IL-6, is released in large amounts during infection, autoimmunity, tissue damage, and cancer." (PMID 35893738, 2022). "MDV/CVI988 infection increased IL-6 mRNA levels in chicken spleens by up to six-fold at 7 dpi and four-fold at 14 dpi." (PMID 36680047, 2022).
infection (continued). "Procalcitonin and interleukin-6 reduction post-treatment of oXiris were most pronounced in infection from skin and soft tissue, urinary and abdominal cavity." (PMID 36249210, 2022). "The blood of mice was collected 12 h after infection and the inflammatory factors (including IL-1β, IL-6, and TNF-α) in serum were measured." (PMID 35493470, 2022). "Our analyses indicated that despite the presence of baseline inflammation, 2 year old mice had significantly lower induction of innate immune genes at 2 days post-infection, including Il6, Ccl4, Cxcl10, Rig-I, Irf7, Ifna2, Oas1b, and Mx2." (PMID 36415465, 2022). "Our analyses indicated that despite the presence of baseline inflammation, 2 yr old mice had significantly lower induction of innate immune genes at 2 days post-infection, including Il6, Ccl4, Cxcl10, Rig-I, Irf7, Ifna2, Oas1b, and Mx2." (PMID 36679892, 2022). "Over and above that, WMC-MDP is capable of rapid, robust, accurate and multiplexed analysis of CRP, PCT, and IL-6 in the dynamic battlefield environment for reliably identifying infections." (PMID 35144683, 2022). "cadC also participates in the regulation of virulence in L. monocytogenes which, in turn, alters the repertoire of proinflammatory cytokines (such as TNF-α and IL-6) produced by the host in response to infection." (PMID 36104331, 2022). "As the inflammatory biomarkers can be used for the differentiation of various organisms, we investigate the performance of C-reactive protein (CRP), procalcitonin (PCT), IL-6, IL-10, TNF-α, and IFN-γ to distinguish infections caused by different pathogens." (PMID 35391735, 2022). "The inflammation of mediators, such as NO, TNF-α, IL-1β, and IL-6, among others, is activated due to the presence of tissue damage or infection; therefore, the concentrations of these mediators increase in the damaged areas." (PMID 35890070, 2022). "When infection, tissue damage or cancer occurs, IL-6 can be rapidly released from monocytes, macrophages and even fat cells." (PMID 35299842, 2022). "IL-6 issues a warning signal as a result of a damage event, such as a tissue injury or an infection, contributing to the host defense by stimulating acute phase responses; however, IL-6 has a pathological effect of chronic inflammation." (PMID 35890070, 2022). "Lenti-Spike infection significantly increased the expression of inflammatory cytokines, including IL-1β, IL-6, and TNF-α, and chemokines, including CCL-2, CCL-3, CCL-4, and CXCL-10, whereas Lipo-hACE2 decoy significantly inhibited all these effects." (PMID 35401811, 2022). "Expression of IL-6 is necessary for recruitment of immune cells to the site of infection, which leads to the ‘cytokine storm’ observed in patients that is associated with poorer outcomes." (PMID 35250984, 2022). "The H4R-mediated activation of mast cells that is induced by histamine leads to the expression of various proinflammatory cytokines and chemokines, such as IL-6, which have been proven to increase the protein levels in mice after infection with PRV." (PMID 35632808, 2022). "The infection caused by APEC in this study led to a significant increase in the expression of IL-1β, IL-6 and TNF-α mRNA in mice brains." (PMID 35900973, 2022). "Infection of cardiomyocytes with the Tulahuén strain of T. cruzi induced an anti-apoptotic effect in an IL-6/STAT-3-dependent manner." (PMID 36389843, 2022). "In order to investigate the possible mechanism underlying HAdV26 induced inflammation, we further explored expression of IL-6 and the corresponding signaling mechanism in relation to HAdV26 infection." (PMID 35458402, 2022). "Infection pathway-related molecules, for example IL-6, TNF, TLR4 and prostaglandins were commonly reported across these studies." (PMID 35379367, 2022). "Various in vitro models have shown the efficacy of bLf in attenuating infection-driven inflammation in epithelial cell models and in reducing IL-6 in LPS-stimulated macrophages." (PMID 35481594, 2022).
infection (continued). "Interleukin-6 (IL-6) is a pro-inflammatory cytokine produced by many types of cells, expressed during states of cellular stress, such as cancer, infection, wound sites, and inflammation." (PMID 36233038, 2022). "IL-6 is produced in response to infection and tissue damage and exhibits a complex biology as it can signal via different modes of action." (PMID 35634332, 2022). "In brief, rMukHN494+495JS infection significantly upregulated the IL-1β level at 24 hpi and the IL-6 level at 12 and 24 hpi compared with rMukteswar infection in the spleen and thymus." (PMID 35711809, 2022). "The secretion level of IL-6 in the coinfection group increased within 6 h and decreased at 24 h of infection." (PMID 35573793, 2022). "The concentration of cytokines in NHBE cells in response to infection in our study indicated that the expression of the proinflammatory cytokines IL-1β, IL-6, and TNF-α was induced by H7N9 infection, but reduced by pdmH1N1 in the early stage of infection." (PMID 35269402, 2022). "As such, the association of either both selected negative predictors (model 2-1: MCP-1_FactorD) or both selected positive predictors (model 2-2: Adiponectin_IL-6) yielded to an outstanding discrimination for the subjects who had previous natural infection." (PMID 36119038, 2022). "Il-6 was also assessed in many studies as a proinflammatory cytokine acting on bone destruction in presence of infection." (PMID 35368315, 2022). "In this study, MAC-T cells were treated with MRSA and MSSA at different time points: The expression of TNF-α, IL-6, phosphorylated p65, and cleaved-Caspase3 expression varies with the time of infection." (PMID 35812882, 2022). "IFN-γ levels were virtually undetectable, while IL-6 levels were significantly elevated on day 6 after infection, which was interpreted by the authors as a high efficiency of the phage in eliminating bacterial cells." (PMID 36211337, 2022). "Here, we have shown that SARS-CoV-2 infection induces the expression of IL-6 by HMEC-1 cells after 24 h from the infection." (PMID 35409421, 2022). "TNF-α, IL-6 and NO production was analyzed from supernatants of each infection at all infection times." (PMID 35531337, 2022). "This is comparable with previously published results, and IL-6 has a high value in distinguishing serious infections in clinical practices." (PMID 35463642, 2022). "Il6 and Tnf mRNAs were significantly upregulated at 24 h.p.i. following infection with the 7:1 Tky/05 HIGH virus." (PMID 36226985, 2022). "We analyzed IL-6 and TNF transcript level, as well as two other ARE-containing RNAs, encoding CXCL8 and COX-2 which were elevated after infection with SARS-CoV-2 and OC43." (PMID 35998203, 2022). "IL-6 is an important cytokine during infection in the body, accompanied with IL-1 and TNF-α, and can be used as an important inflammatory marker for both acute and chronic inflammatory responses." (PMID 36290585, 2022). "C-reactive protein (CRP), an acute-phase inflammatory protein is primarily synthesized and stored in hepatocytes, and released in response to infection and inflammation, primarily with the stimulation of IL-6 followed by IL-1 and tumor necrosis alpha (TNF-α)." (PMID 35683357, 2022). "Infection of mice with systemic il6 gene knockout (KO) with a high dose of virulent M. tuberculosis via intravenous (i." (PMID 35154093, 2022). "Following infection, they secrete IL-6 promoting proinflammatory responses and proteasomal degradation of Zonula Occludens-1 (ZO-1), thus participating in JEV-induced BBB impairment." (PMID 35887383, 2022). "IL-6 is transiently expressed in response to environmental stressors such as infection and tissue damage." (PMID 36613892, 2022). "IL-6 is thought to play a role in thermoregulation by contributing to maintenance of core temperature, as well as initiating a fever response during infection." (PMID 36053365, 2022).
infection (continued). "Through repeated comparison, we found that several cytokines, including IL-1 (interleukin-1), IL-6 (interleukin-6), TNF-α (tumor necrosis factor-α), and IFN-γ (interferon-γ), always coexist and are critical to CRS caused by infection or immunotherapy." (PMID 35431655, 2022). "Interleukin 6 (IL-6) is a soluble mediator that is rapidly produced in the acute phase of infection or tissue damage, and promotes host defense by stimulating hematopoiesis, acute phase inflammation and immune response." (PMID 35299842, 2022). "H. pylori colonization intensity and Lewis antigens were significantly higher in GES-1 than in HSFE cells, whereas IL-8 and IL-6 levels were significantly higher in HSFE than in GES-1 cells after infection." (PMID 35350782, 2022). "The same results were also evident with respect to emerging indicators for infection assessment such as IL-6 and endotoxin." (PMID 36760236, 2022). "IL-6 is produced by B and T lymphocytes during the acute phase of an infection, as well as monocytes, endothelial cells, and fibroblasts." (PMID 35449688, 2022). "Interleukin-6 not only regulates hepatic ZIP14 but also contributes to hypozincemia of the acute-phase response to infection and inflammation." (PMID 35330104, 2022). "In the HK, however, the transcription levels of il1b, il6, and il8 were up-regulated upon infection." (PMID 35055122, 2022). "IL-6 is a proinflammatory cytokine that is increased rapidly in response to acute inflammation and is proportional to the degree of injury and infection." (PMID 35624447, 2022). "TNF-α is a primary inflammatory factor released in the skin after trauma, injury, or infection and triggers the expression of other pro-inflammatory cytokines including IL-6, IL-8, and IL-1β." (PMID 36432834, 2022). "While RSV-induced IL-6 and IL-8 production usually requires CNS cells infection, SIV appears quite effective in inducing high levels of these cytokines without the direct invasion of the nervous system." (PMID 36412662, 2022). "We found that infection of primary macrophages with influenza PR8 or CA09 led to a robust increase in both IL-6 and TNFα." (PMID 34899695, 2021). "And IL-6 is a pleiotropic cytokine that participate in infection, playing a role in antiviral effect through activating the JAK-STAT signaling pathway." (PMID 33797313, 2021). "We then evaluated the effects of knockdown on HRV16-induced IL-6 and IL-8 release as compared to the non-infection control in each group." (PMID 34001091, 2021). "Results from our infection model suggest that EBERs stimulate the expression of IL-6 to some extent, but the viral miRNAs largely repress IL-6 secretion." (PMID 33785626, 2021). "IL-6 is usually described as a pleiotropic cytokine produced in response to tissue injury or infection." (PMID 33786327, 2021). "Compatible with the data obtained from analyzing the TRIF KD and KO, both TLR3 and TLR4 proved to be required for optimal production of IL-6 following infection with L. pneumophila." (PMID 34280250, 2021). "Six hours after infection, N4bp1−/− mice had significantly elevated serum concentrations of IL-6 compared to wild-type mice." (PMID 33654074, 2021). "The production of CXCL1, IL-1β, TNF, and IL-6 was decreased in the lungs of Trem1−/- mice at early stages on the infection (2 dpi)." (PMID 33525982, 2021). "It is a potent inducer of the acute phase response and a rapid production of IL-6 contributes to host defence during infection or injury." (PMID 33669522, 2021). "The fluctuation in WBC count and TNF-α, IL-6 and IL-1β content in rat blood during the first week after infection were also monitored." (PMID 34521472, 2021). "The mRNA expression levels of IFN-γ, and the interleukins (ILs) IL-10 and IL-6 were also significantly upregulated in the infected animals at day 5 post-infection." (PMID 34370799, 2021).